CTLA4 (cytotoxic T-lymphocyte associated protein 4)
Diseases named in the same sentence as CTLA4 in open-access papers (continued):
Sharing a sentence is not in itself a finding about the gene and the disease.
sarcoma (continued). "A similar remodeling of intratumoral macrophages was observed in a murine sarcoma model treated with anti-PD1/anti-CTLA-4 antibodies." (PMID 33329573, 2020). "Numerous studies combining CTLA-4 inhibition with immunotherapy, tyrosine kinase inhibitors, or chemotherapy are ongoing for sarcoma patients (ie Trabectedin, Ipilimumab and Nivolumab (NCT03138161), Ipilimumab and Imatinib (NCT01738139)." (PMID 31395100, 2019). "Based on this theoretical background, numerous clinical trials were attempted in sarcoma patients with various immunomodulatory agents such as macrophage-colony stimulating factor (GM-CSF), peptide vaccines, and anti-CTLA-4 antibody." (PMID 27393385, 2016). "Increased expression of CTLA-4 was seen in both T cells in sarcoma patients as compared to HV (p = 0.05)." (PMID 26286851, 2015). "Similar results were obtained in NSCLC patients given a PD-1 antibody and in chemically induced mouse sarcomas treated with anti-CTLA-4 and/or anti-PD-1 antibodies." (PMID 26343195, 2015). "Monoclonal antibody therapies against tumor antigens such as disialoganglioside GD2 or immune checkpoint targets such as CTLA-4 and PD-1 are being actively explored in pediatric sarcomas." (PMID 26301204, 2015). "Radiotherapy and chemotherapy for pleomorphic sarcoma are recommended as adjuvant therapies, and immunotherapy such as ipilimumab (anti-CTLA4), nivolumab (anti-PD1), and pembrolizumab (anti-PD1) are the current treatment modalities for this type of sarcoma; our patient did not undergo immunotherapy." (PMID 40351983, 2025). "The first trials to use ICI in sarcomas either as monotherapy with programmed death-1 (PD-1) or programmed death-ligand 1 (PD-L1) inhibitors, or in combination with CTLA-4 inhibitors, demonstrated limited efficacy in unselected sarcoma population with some isolated radiological responses." (PMID 40495323, 2025). "In support of this observation, longitudinal sampling of murine sarcoma treated with anti-PD-1/anti-CTLA-4 suggested that macrophage activation following ICB was due to effects on circulating monocytes and early macrophages entering tumours, rather than mature intratumoural macrophages." (PMID 40523200, 2025). "ORR to combination ICI (PD-1/PD-L1 and CTLA4 inhibitors) is moderately higher in sarcoma patients." (PMID 40495323, 2025). "Additionally, we collected two external independent immunotherapy cohorts (anti-PD-1/PD-L1/CTLA-4) and a cohort of late-stage sarcoma patients who received immunotherapy at our hospital to evaluate the performance of DRGs in predicting immunotherapy response." (PMID 38531930, 2024). "In a mouse model of sarcoma, it has been shown that monoclonal antibody blockade of CTLA-4, PD-1, or PD-L1 augments glucose availability in the TME and glycolytic metabolism in T cells by restoring mTOR-mediated signaling, as well as the activity of the enzyme glutamate dehydrogenase (Glud1)." (PMID 36713558, 2022). "Although there is no well-established relationship between the expression of PD-1/PD-L1/CTLA-4 genes and the prognosis of patients with sarcomas, their interaction and extent of immune cell infiltration into sarcomas are probably the key determinants of therapeutic response." (PMID 36147250, 2022). "Therefore, based on various databases, this study analyzed the expression of PD-1, PD-L1, and CTLA-4 in patients with pan-cancer and sarcoma." (PMID 36147250, 2022). "Sarcoma patients have T cells with high CTLA-4 expression within the tumor and peripheral blood." (PMID 33381449, 2020). "Although three–four cycles of anti-CTLA-4 antibody are administered in clinical trials of sarcoma and other tumor patients, we administered three cycles of anti-CTLA-4 antibody in the present study based on previous preclinical reports, allowing us to compare our data with other reports." (PMID 32545427, 2020).
sarcoma (continued). "It was demonstrated that treatment with a synthetic monoclonal antibody against cytotoxic T-lymphocyte-associated protein 4 (CTLA-4, ipilimumab) could control established MCA205 sarcomas in mice with healthy gut bacteria." (PMID 30263059, 2018). "However, even in animal models, as shown in the early studies by Allison’s group, it was not established the quantity and quality of TAAs targeted in mice in which regressions of the transplantable B16 melanoma or sarcomas after CTLA-4 blockade were observed." (PMID 26343195, 2015). "Immune checkpoint inhibitors (CPIs) targeting the PD-1 and CTLA-4 axes have demonstrated promising responses in a select number of STS subtypes, including rarer subtypes, such as alveolar soft part sarcoma, SWI/SNF-deficient sarcomas, clear cell sarcoma, and angiosarcoma." (PMID 35327375, 2022). "Preclinical studies have demonstrated expression of PD-1L in OS and suggest that high expression levels may correlate with worse clinical outcomes; In vivo studies using murine sarcoma models with anti-CTLA-4 antibodies have also shown promise for these agents." (PMID 26301204, 2015). "Furthermore, monoclonal antibodies could be designed to block checkpoint receptors like CTLA-4 or PD-1, which are more abundant in non-translocation-associated sarcomas (such as six of the TCGA subtypes analyzed here, excluding SS)." (PMID 37834179, 2023). "Since adult malignancies showed a good response to a combination of PD-L1 and CTLA-4 inhibition, a recently completed pediatric phase I/II trial (NCT02304458) combined ipilimumab and nivolumab to treat R/R sarcomas and included R/R NB." (PMID 38140246, 2023). "Gives insight on groundbreaking advances in the immune-therapeutic field, as well as the possible applications of immunological therapies in sarcomas, including ICB via modification of the axis in CTLA-4 and PD-1, plus therapies with ACT." (PMID 34725602, 2021). "RNA-seq of TILs from progressor sarcoma tumors in mice that were either treated with control, anti-CTLA-4, anti-PD-1 blocking antibodies, or a combination of anti-CTLA-4 and anti-PD-1 antibodies revealed differential gene enrichment." (PMID 28443090, 2017). "Sarcoma patients had increased expression of CTLA-4, a T-cell inhibitory receptor, on both CD4 (38 % sarcoma vs. 16 % HV; p = 0.05) and CD8 T cells (37 % sarcoma vs. 12 % HV; p = 0.05) as compared to HV." (PMID 26286851, 2015). "We have identified several immune phenotypes that are altered in pediatric sarcomas including elevated CD14+ HLA-DRlo/neg cells, elevated CTLA-4+ T cells, and decreased CD4 T cells." (PMID 26286851, 2015). "Anti-CTLA4 antibody ipilimumab in monotherapy showed negative results in recurrent synovial sarcoma and pediatric sarcoma." (PMID 37190214, 2023). "In conclusion, our study elucidates that differential expression of PD-1/PD-L1/CTLA-4 on sarcoma cells is not an independent prognostic factor in sarcoma nor mutation frequency." (PMID 36147250, 2022). "A completed phase I trial (NCT00556881) of the anti-CTLA-4 drug ipilimumab in children and adolescents with treatment-resistant cancer included sarcomas, but no results have been reported yet." (PMID 34178688, 2021). "The role of targetable immune checkpoint proteins such as CTLA-4 or PD-L1 in sarcomas is not yet well characterized but is a subject of active investigation." (PMID 34178688, 2021). "Phase I and II studies of ipilimumab, a CTLA-4 blocking mAbs, in pediatric patients with advanced solid tumors (including sarcomas) showed tolerability but no objective clinical or radiologic responses as monotherapy (NCT01445379)." (PMID 33381449, 2020). "Previous analyses of transcriptomic data from antigen specific T cells in a checkpoint responsive murine sarcoma model have defined alterations in metabolic, signaling and T cell effector pathways after treatment with anti-PD1, anti-CTLA-4 or combination therapy." (PMID 29423108, 2018).
sarcoma (continued). "Administration of anti-CTLA-4 antibodies was demonstrated to result in a CD8+ T-cell-dependent tumour rejection and treatment doubled the numbers of mLama4- and mAlg8-specific T cells infiltrating the tumours of MCA sarcoma-bearing mice." (PMID 28916749, 2017). "Increased expression of the inhibitory T cell receptor CTLA-4 on CD4 and CD8 T cells in sarcoma patients may have direct implications for immune therapy." (PMID 26286851, 2015). "We previously demonstrated that anti-CTLA-4 and/or anti-PD-1 induces macrophage TME remodeling characterized by a reduction in M2-like macrophages co-expressing the fractalkine receptor (CX3CR1) and CD206 and an increase in M1-like iNOS+ macrophages in mouse MCA sarcoma models." (PMID 38187708, 2024). "While these pathways have been described as potential targets for treament of sarcomas, not all patients may respond to such approaches, as, for example, was recently shown for treatment with a CTLA4 inhibitor in synovial sarcoma." (PMID 37492373, 2023). "Although immune checkpoint blockade molecules, anti-CTLA-4 antibody and anti-PD-1 antibody, have not been proven currently to have the effectiveness, there is too little information to decide efficacy of ipilimumab and nivolumab in sarcomas." (PMID 26167500, 2015). "Therefore, it may be premature to rule out the role of CTLA-4 in sarcoma based on the study design of this pilot trial." (PMID 27703409, 2016). "Combination therapies utilizing CTLA-4 and PD-L1 mAb blockade in early phase clinical studies have shown synergistic slowing of disease progression and extended PFS in adults with metastatic or unresectable sarcomas; however, they have not been tested in children (NCT02500797)." (PMID 33381449, 2020).
osteosarcoma (68 papers, 2012 to 2025). A usually aggressive malignant bone-forming mesenchymal neoplasm, predominantly affecting adolescents and young adults. "Cytotoxic T-lymphocyte associated protein 4 (CTLA-4) rs5742909 was significantly associated with osteosarcoma risk under the homozygous model (TT vs. CC) OR 2.5 95% CI = 1.4–4.4, P = 0.032." (PMID 38360742, 2024). "Our main analysis identified significant associations with osteosarcoma for 12 variants in 8 genes: CTLA-4, ERCC3, IL-8, PRCKG, RECQL5, TNF-α, XRCC3, and VEGF." (PMID 38360742, 2024). "When studies deviating from Hardy–Weinberg Equilibrium (HWE) were omitted, CTLA-4 rs231775 emerged as significantly associated with an increased risk of osteosarcoma." (PMID 38360742, 2024). "Polymorphism in the CTLA-4 gene (rs231775) increased malignancy in osteosarcoma and Ewing sarcoma since the affinity with B7-1 molecule was significantly increased and concurrently, effector T-cell function was diminished." (PMID 37605389, 2024). "CTLA-4 is significantly associated with carcinogenesis of osteosarcomas, which provides a potential therapeutic target." (PMID 31156651, 2019). "CTLA4 haplotypes has also been documented in association with susceptibility to develop esophageal squamous cell carcinoma and osteosarcoma." (PMID 22911710, 2012). "Studies have identified common SNPs in genes important for growth and tumor suppression, hypothesized to modify osteosarcoma susceptibility, such as CTLA-4, ERCC2, and TP5316–18." (PMID 38360742, 2024). "Currently, several meta-analyses consistently show that CTLA-4 is significantly associated with osteosarcoma risk, and might play an important role in carcinogenesis of osteosarcoma." (PMID 27683579, 2016). "In osteosarcoma, accumulating data suggest a link between heightened CTLA-4 expression and disease progression, potentially mediated through mechanisms involving IDO induction, reduced T cell proliferation, and altered inflammatory cytokine signaling." (PMID 41244900, 2025). "Preclinical and clinical studies investigating CTLA-4 inhibitors in osteosarcoma have yielded limited but promising insights." (PMID 40170852, 2025). "Recent study showed that combining anti-CTLA-4 with CD103+ cDC1 dendritic cell vaccine therapy increased cDC vaccine efficacy against osteosarcoma lung metastases." (PMID 41244900, 2025). "The most widely studied immune checkpoints in osteosarcoma include PD-1/PD-L1 pathway and the CTLA-4 pathway." (PMID 40170852, 2025). "Metastatic osteosarcoma mouse model showed complete tumor control and prevented immune escape in 50% of cases with PD-L1/CTLA-4 blockade." (PMID 41383602, 2025). "Anti-CTLA-4 antibodies paired with dendritic cell vaccines improved responses in osteosarcoma models, while ICIs augmented CAR-T cell activity by reversing T cell exhaustion." (PMID 41383602, 2025). "Findings from an observational study have shown that increased CTLA4 T cells were found in aggressive pediatric osteosarcoma patients." (PMID 39081321, 2024). "Using single-cell sequencing technology, another observational study revealed that exhausted T cells exhibited substantial infiltration and a progressive increase in expression of CTLA4 in osteosarcoma samples." (PMID 39081321, 2024). "The pooled ORs of 12 variants in 8 genes (CTLA-4, ERCC3, IL-8, PRCKG, RECQL5, TNF-α, XRCC3, and VEGF) were significantly associated with the risk of osteosarcoma in the main analysis." (PMID 38360742, 2024). "In prior meta-analyses, associations of genetic polymorphisms in VEGF, MDM2, CTLA-4, TNF-a, TNF-b1, PRCKG, RECQL5, XRCC3, and GST with osteosarcoma susceptibility were investigated." (PMID 38360742, 2024). "A report has sown an upregulated expression of CTLA-4 on the surface and cytoplasmic compartments of different pediatric cancer cells of neuroblastoma, osteosarcoma, and rhabdomyosarcoma." (PMID 37605389, 2024).
osteosarcoma (continued). "CTLA-4 (cytotoxic T-lymphocyte antigen-4) is a glycoprotein co-inhibitory receptor involved in T-cell activation, which is expressed in osteosarcoma cells, among other types of malignancies." (PMID 39417976, 2024). "Recent trials have explored the efficacy of PD-1 and CTLA-4 targeted immunotherapies in osteosarcoma." (PMID 38915446, 2024). "Hypoxia can promote the expression of immune checkpoint molecules such as PD-1 and CTLA-4, which can inhibit the function of infiltrating immune cells and promote immune escape of osteosarcoma cells." (PMID 37497349, 2023). "For example, some studies have shown that by inhibiting immunosuppressive pathways such as PD-1/PD-L1 and CTLA-4, the ability of immune cells to attack osteosarcoma cells can be restored, thereby improving the efficacy of immunotherapy." (PMID 37497349, 2023). "They combined CTLA-4 with a PD-1 antibody in a K7M2 murine model of metastatic osteosarcoma, and the tumor progression was under control." (PMID 36232719, 2022). "In some previous research, CTLA-4 and PD-1/PD-L1 are identified to overexpress in osteosarcoma and negatively correlate to the prognosis." (PMID 34094974, 2021). "Based on these results, we evaluated the efficacy of BEMPEG, alone and in combination with anti‐PD‐1 and/or anti‐CTLA‐4 ICIs in metastatic and orthotopic murine models of osteosarcoma." (PMID 33152115, 2021). "Blockade of PD-1 or CTLA-4 can contribute to the inhibition of osteosarcoma, but, in a phase II trial, only 5% of patients with osteosarcoma were relieved by PD-1 inhibitor-pembrolizumab." (PMID 34094974, 2021). "What’s more, they also found combining with CTLA-4 blockade in a mouse osteosarcoma model, the anticancer effect had been enhanced: more CTLs, less Treg, prolonged survival, etc.." (PMID 34094974, 2021). "GSEA revealed enrichment of gene sets associated with the CTLA4 pathway, TOB1 pathway, cell aggregation, antimicrobial humoral immune response, and EMT in high-risk osteosarcoma patients." (PMID 34095215, 2021). "Anti‐PD‐1 and anti‐CTLA‐4 each suppressed the growth of DLM8 osteosarcoma compared to vehicle control, leading to respective TGI of 57% (P < .01) and 79% (P < .0001) and 86% (P < .0001) for the combination." (PMID 33152115, 2021). "In preclinical murine models of osteosarcoma, when used alone or in combination with other therapies, antibodies against CTLA‐4 or PD‐1 have shown benefit by upregulating the antitumor activity of cytotoxic T cells." (PMID 33152115, 2021). "It was found that there was a significant relationship of the risk score with important immune checkpoints expressions (CTLA4, PDL1, TIM3, LAG3, TIGIT) in osteosarcoma patients." (PMID 34335109, 2021). "Several immunotherapeutic approaches have shown benefit in murine osteosarcoma models, including the anti‐programmed death‐1 (anti‐PD‐1) and anti‐cytotoxic T‐lymphocyte antigen‐4 (anti‐CTLA‐4) immune checkpoint inhibitors." (PMID 33152115, 2021). "This is in line with the finding that osteosarcomas with high levels of immune infiltration are enriched in immune downregulation pathways, including PD-1 signalling and the CTLA-4 pathway." (PMID 32961800, 2020). "In recent years, some investigations proposed that immune checkpoint blockage such as CTLA‐4 and PD‐L1 inhibits progression of osteosarcoma by stimulating CD8 + T cell." (PMID 32820615, 2020). "Immune checkpoint-based immunotherapy, including the programmed cell death receptor-1 (PD-1) and its ligand (PD-L1) along with CTLA-4, represents a novel therapeutic strategy for osteosarcoma patients." (PMID 32194840, 2020). "In a study looking at CTLA-4 expression on a panel of 34 paediatric and adult tumour cell lines, including osteosarcoma and rhabdomyosarcoma, 30 of 34 cell lines showed positive CTLA-4 staining." (PMID 33207697, 2020).